MIR1302-6 (microRNA 1302-6)
Synonyms: hsa-mir-1302-6; MIRN1302-6
Gene: MicroRNA gene on chromosome 7 (18,127,220 to 18,127,309, reverse strand). Ensembl gene ENSG00000221393.
Homologues: Paralogues in human: MIR1302-1 (63% identical), MIR1302-8 (54% identical).